ERAP1 (endoplasmic reticulum aminopeptidase 1)
Diseases named in the same sentence as ERAP1 in open-access papers (continued):
Sharing a sentence is not in itself a finding about the gene and the disease.
autoimmune disease (continued). "Here, the authors assess ERAP1 conformational states in solution, providing insight into the molecular mechanisms of ERAP1 substrate-length dependent catalytic activity and regulation, including the effects of autoimmune disease-associated polymorphism." (PMID 34489420, 2021). "Importantly, allelic variants of ERAP1 leading to missense mutation increase the capability of ERAP1 to induce inflammation in autoimmune diseases." (PMID 31577850, 2020). "Such a role may explain why ERAP1 has been implicated by GWAS in the pathogenesis of autoimmune diseases that may be precipitated by aberrant responses to pathogen encounters." (PMID 23894499, 2013). "Our data suggest that the strong genetic associations between ERAP1 polymorphisms and various autoimmune diseases may be linked to ERAP1’s role in innate immune regulation, including regulating proinflammatory cytokine and chemokine responses during inflammasome activation." (PMID 35246034, 2022). "Thus, the association of ERAP1 and autoimmune diseases may be mediated by its role in regulating NK cell development, maturation, as well NK roles in acute innate immune responses." (PMID 23894499, 2013). "Variation in ERAP1 and ERAP2 genes underwent selection during the Black Death and impact autoimmune disease susceptibility." (PMID 41428259, 2025). "We observed no significantly altered burden of functionally impactful variation across these groups for ERAP1 (CD vs CD and ≥ 1 autoimmune disease diagnosis p = 0.376, UC vs UC and ≥ 1 autoimmune disease diagnosis p = 0.369)." (PMID 41428259, 2025). "Another key player in autoimmune diseases is endoplasmic reticulum aminopeptidase 1 (ERAP1), a member of the M1 family of aminopeptidases." (PMID 41385507, 2025). "ERAP2 is known to be an aminopeptidase involved in the pathophysiology of autoimmune diseases, and the ERAP2/ERAP1 ratio results has been linked to increased autoimmunity risk." (PMID 40574847, 2025). "The ERAP1/ERAP2/LNPEP aminopeptidases are involved in antigen processing and variation is linked to multiple autoimmune diseases." (PMID 38421405, 2024). "ERAP1 plays a significant role in the pathogenesis of various human diseases, including autoimmune diseases, cancer, atopic dermatitis, viral infections, and hematological disorders." (PMID 38534723, 2024). "By utilizing in vitro and in vivo murine models, we can further study the role of ERAP1 in autoimmune diseases." (PMID 35246034, 2022). "The previous studies have shown that ERAP1 is dysregulated in autoimmune diseases, cancer, and several types of viral disease including HIV, lymphocytic choriomeningitis virus (LCMV), and human cytomegalovirus (HCMV)." (PMID 35602060, 2022). "IFI30 has been implicated in the pathogenesis of some autoimmune diseases, and genetic polymorphisms of ERAP2 and its paralog ERAP1 are associated with increased susceptibility to autoimmune/chronic inflammatory disorders." (PMID 35954309, 2022). "Genetic variants of ERAP1 and ERAP2 genes can increase the susceptibility to autoimmune diseases, cancer and infectious diseases." (PMID 33679890, 2021). "The validation of ERAP1 as a drug discovery target in autoimmune disease and cancer still requires the development of potent, permeable and selective chemical tools." (PMID 33887439, 2021). "The ERAP1 roles against virus infection or in autoimmune disease mechanisms through peptide trimming has been investigated in several studies." (PMID 33250919, 2020). "Recent genome-wide association studies (GWAS) have proven the importance of ERAP1 and ERAP2 genes in conferring susceptibility of individuals to different autoimmune diseases and their linkage with particular MHC class I alleles." (PMID 22942706, 2012). "ERAP1 SNP rs26618, located in the third position in codon 276, was hypothesized to affect the structure and function of ERAP1 in autoimmune diseases, although this hypothesis lacks experimental data." (PMID 38596688, 2024).
autoimmune disease (continued). "Therefore, modulationof ERAP1 activity has potential therapeutic indications for cancerimmunotherapy and in autoimmune disease." (PMID 39691536, 2024). "On the other hand, the lack of ERAP2 may, in many instances, prevent it from overtrimming antigenic peptides produced by ERAP1, which are necessary to fight infection or contribute to autoimmune disease." (PMID 35769458, 2022). "In addition, the endoplasmic reticulum aminopeptidase 1 (ERAP1) gene, which is involved in antigen presentation and associated with inflammatory bowel disease and a number of other autoimmune diseases, appeared in two associations." (PMID 29378630, 2018). "An ERAP1 risk haplotype may increase the production of an autoantigenic peptide, leading to its presentation by HLA-C*06:02 and the activation of CD8+ T cell, which triggers autoimmune disease." (PMID 38898675, 2024). "Mann–Whitney U tests were conducted to compare GenePy scores for ERAP1 and ERAP2 between those with isolated CD and CD and ≥ 1 autoimmune disease diagnosis and those with isolated UC and UC and ≥ 1 autoimmune disease diagnosis." (PMID 41428259, 2025). "ERAP1 and ERAP2 play crucial roles in the modulation of the immune response, making them attractive targets for therapeutic intervention, especially in autoimmune diseases." (PMID 40226591, 2025). "However, our results suggest that a non-MHC role of ERAP1, that involves initial innate immune system modulation, as well responses to pro-inflammatory stimuli may also be playing a role in these autoimmune disease associations." (PMID 23894499, 2013). "Notably, three genes, namely ERAP1, ERAP2, and LNPEP, hold significant roles in human pathology, especially concerning autoimmune diseases." (PMID 38534723, 2024). "Indeed, increased ERAP1 and ERAP2 expression was demonstrated to raise the odds of developing a number of autoimmune diseases such as Chron, Beçhet’s disease, Birdshot Chorioretinopathy and Type I diabetes." (PMID 39839670, 2024).
Behçet’s disease (24 papers, 2013 to 2025). "Pathogenic interactions have also been shown between ERAP1 and the HLA-B51 protein in Behcet’s disease." (PMID 38892265, 2024). "There is, for example, a well-known epistatic effect of the ERAP1 (endoplasmic reticulum aminopeptidase 1) gene to the HLA-B51 association with Behçet’s disease." (PMID 37937194, 2023). "After that, the polymorphisms in ERAP1 have also been found to be associated with Behcet's disease by genome-wide association studies, and since then, replication studies were performed by researchers all over the world." (PMID 34395615, 2021). "Strikingly, allotype 10, previously associated with Behçet's disease, is consistently a low-activity outlier, suggesting that a significant percentage of individuals carry a subactive ERAP1 gene." (PMID 33617882, 2021). "The association of ERAP1 with diseases in the context of specific HLA class I alleles is also observed in the cases of Behçet disease (BD) and Psoriasis." (PMID 25566501, 2014). "HLA-B*51 and ERAP1 affect the risk of developing Behçet's disease (BD)." (PMID 32161166, 2020).
melanoma (20 papers, 2012 to 2025). A malignant, usually aggressive tumor composed of atypical, neoplastic melanocytes. "Using the coefficients obtained by multivariate Cox analysis, the risk score of melanoma patients was calculated according to the following formula: risk score = (−0.097) × A2M + (−0.185) × NAMPT + (−0.123) × LIF + (−0.247) × EBI3 + (−0.170) × ERAP1." (PMID 35326741, 2022). "However, a recent study identified a novel ERAP1 mutation in human melanoma cell lines." (PMID 26146606, 2015). "We find that in the A375 melanoma cell line, ERAP1 functional disruption appears to affect the capability of the ER to respond to redox challenges." (PMID 40189142, 2025). "Recently, Leishman and colleagues reported that inhibition of ERAP1 in “hot” tumor models, such as melanoma and colorectal cancer, results in the generation of new epitopes derived from several cancer-associated proteins." (PMID 39438988, 2024). "Heterogeneous variations of ERAP1 and 2, from high to low levels, were identified in 28 melanoma cell lines compared to primary melanocyte cell lines." (PMID 38534723, 2024). "Previously, this approach helped us to exclude incorrect normalizations and biological misinterpretations concerning the alteration of ERAP1 gene expression during melanoma progression." (PMID 35228606, 2022). "The immunohistochemical results of the Human Protein Atlas dataset demonstrated that four hub genes (A2M, NAMPT, LIF, and ERAP1) are overexpressed in melanoma tissues." (PMID 35326741, 2022). "The authors show that both genetic and pharmacological inhibition of ERAP1 strongly increase MART-126-35 presentation in human melanoma cells and IFN-γ release by MART-126-35-specific CD8+ T cells." (PMID 35936007, 2022). "Since ERAP1 overexpression had already been associated with the elimination of immunodominant epitopes from melanoma and colorectal carcinoma, the study focused on defining the role of ERAP1 upregulation in antigen presentation in HPV16-induced carcinomas." (PMID 32183384, 2020). "In melanoma, ERAP1 has a destructive role for many epitopes." (PMID 38534723, 2024). "Although a previous study has investigated the underlying mechanisms of ERAP1 downregulation in melanoma cell lines, no investigations in clinical specimens have been performed to date." (PMID 26146606, 2015). "Interestingly, no ERAP1 mutations were found in any mEGFR tumors or comparable TCGA data from melanoma patients (data not shown), suggesting its function is essential in multiple cancer types." (PMID 36092893, 2022). "Similar to primary melanoma cells, loss of IRF2 dropped the surface expression of MHC I and significantly reduced transcripts of TAP2, ERAP1, and PSME1 detected in B16F0 mouse melanoma cells." (PMID 39281881, 2024). "James and Keller found that ERAP1 inhibition leads to a potent antitumor cytotoxic response of CD8+ T cells in a mouse model of colon cancer and a human melanoma cell line, respectively." (PMID 39438988, 2024). "The influence of APP components on cancer cell sensitivity to immune pressure differs between the two cancer models, with ERAP1, calreticulin and TAPBPR more relevant in melanoma, and β2m in renal carcinoma." (PMID 35936007, 2022). "ERAP1 and ERAP2 expression is also frequently altered in melanoma, acute myeloid leukemia, gastric adenocarcinoma, HPV-induced malignancies and renal clear cell carcinoma, as another immune escape mechanism." (PMID 33499248, 2021). "In another study, a heterogeneous expression of ERAP1 and ERAP2 was detected in a panel of 28 melanoma cell lines." (PMID 25566501, 2014). "In one study, expression of ERAP1 and ERAP2 was detected in all tumor cell lines examined, including melanoma and various type of carcinomas, although at highly variable levels and independently of each other." (PMID 25566501, 2014). "In a recent study, heterogeneous expression of ERAP1 and ERAP2, ranging from high to very low levels, was detected in 28 melanoma cell lines as compared to primary melanocytes." (PMID 22942706, 2012).
melanoma (continued). "Moreover, the RT-PCR analysis in our clinical samples demonstrated that EBI3, ERAP1, and NAMPT mRNA expression levels were significantly upregulated in melanoma tissues compared to normal tissues." (PMID 35326741, 2022). "Indeed, altered ERAP1 expression influences the effectiveness of cytotoxic CD8+ T-cell anti-tumor immune responses in the context of solid cancer, melanoma and a T-cell lymphoma mouse model." (PMID 33499248, 2021). "We found that ERAP1 and ERAP2 were expressed in essentially all tumor cell lines examined (melanomas, leukemia-lymphomas and carcinomas of breast, colon, lung, chorion, skin, prostate, cervix, kidney and bladder) at highly variable levels and independently of each other." (PMID 22942706, 2012). "Moreover, this study may explain the imbalance between ERAP1 and ERAP2 observed in various tumor cell lines, such as leukemia, lymphoma, carcinoma, and melanoma, and in tumor-transformed tissues of the breast, ovary, lung, colon, and thyroid." (PMID 37372322, 2023). "The results demonstrated that EBI3, ERAP1, and NAMPT mRNA levels were upregulated in melanoma tissues, while A2M and LIF were not insignificant." (PMID 35326741, 2022).
cervical carcinoma (15 papers, 2012 to 2025). A carcinoma arising from either the exocervical squamous epithelium or the endocervical glandular epithelium. "In cervical cancer, SNPs rs27044, rs26618, and rs26653 in ERAP1 and rs2287988 in ERAP2 influence susceptibility to this tumor form." (PMID 38534723, 2024). "In another study, in cervical carcinoma patients, partial ERAP1 loss was significantly associated with reduced 5-year overall survival (OS), disease free survival, and the presence of lymph node metastases." (PMID 37101107, 2023). "In an earlier report, the same authors showed that low ERAP1 expression was significantly associated with reduced survival of patients with cervical carcinoma." (PMID 34149699, 2021). "According to this, several ERAP1 polymorphisms were described as affecting susceptibility to cervical carcinoma in Dutch and Indonesian populations." (PMID 34149699, 2021). "In a single study concerning cervical carcinoma, Mehta and colleagues analyzed the influence of several SNPs in ERAP1 (including rs30187) on disease risk and OS." (PMID 34149699, 2021). "The ERAP1 haplotype, rs27044C-rs30187T-rs26618T-rs26653G-rs3734016C, was associated with a lower risk of cervical cancer (P = 0.001; OR = 0.804, 95% CI: 0.711–0.910)." (PMID 32321463, 2020). "In particular, we have previously shown that downregulation of TAP1, LMP7 and ERAP1 expression is associated with decreased survival in HPV-mediated cervical carcinoma in Dutch patients." (PMID 25796583, 2015). "In particular, the combination of a minor allele at ERAP1-575 and a major allele at ERAP1-730 was most significantly associated with increased cervical carcinoma risk, the PAF for this haplotype being 4.6 %, as calculated using Miettinen’s formula." (PMID 25796583, 2015). "Specifically, the combination of a minor allele at ERAP1-575 with major alleles at both TAP2 loci was associated with an increased risk of cervical cancer; the PAF for this haplotype was 3.9 %." (PMID 25796583, 2015). "We have demonstrated that various single nucleotide polymorphisms (SNPs) in the LMP7, TAP2 and ERAP1 genes were significantly associated with risk of developing cervical carcinoma in the Dutch population." (PMID 25796583, 2015). "Defective expression of the APM component ERAP1 is associated with progression and poor clinical outcome in cervical carcinoma." (PMID 26146606, 2015). "In the first study, the authors identified two common ERAP1 polymorphisms, R127P and Q730E, significantly associated with increased risk of cervical cancer." (PMID 25566501, 2014). "In a subsequent study, the same group investigated which genetic ERAP1 variation affected tumor progression and overall survival in cervical carcinoma patients, and provided the first indication of association of ERAP1 SNPs with ERAP1 protein expression." (PMID 25566501, 2014). "Variants of ERAP1 have been associated with decreased survival in cervical carcinoma, with ERAP1 loss being an independent predictor for survival, possibly due to the role of ERAP1 as a key determinant of the repertoire of MHC class I-presented peptides." (PMID 22942706, 2012). "A previous study reported that any G allele in ERAP1 rs26654 allele might be associated with a lower risk of cervical cancer compared with C/C carriers (p = 0.001)." (PMID 40141198, 2025). "ERAP1/ERAP2 polymorphisms have been associated with cervical cancer and autoimmunity." (PMID 37173324, 2023). "Additionally, haplotype analysis results showed that the ERAP1 haplotype, rs27044C-rs30187T-rs26618T-rs26653G-rs3734016C, was associated with a lower risk of cervical cancer (P = 0.001)." (PMID 32321463, 2020). "In addition, they found that up to 12% of all cervical carcinomas correlated with a particular haplotype combination that include the minor allele at the ERAP1-127 and ERAP1-730 loci, and the major allele at the TAP2-651 and LMP7-145 loci." (PMID 32183384, 2020).